MT4 (metallothionein 4)
Description:
Seems to bind zinc and copper. Could play a special role in regulating zinc metabolism during the differentiation of stratified epithelia.
Synonyms: MT-4; MT-IV; MTIV
Tractability: No criterion of Open Targets' tractability assessment is met for any kind of drug.
Gene: Protein-coding gene on chromosome 16 (56,565,073 to 56,568,957, forward strand). Ensembl gene ENSG00000102891.
Pathways (Reactome):
Cellular responses to stimuli: Metallothioneins bind metals
Gene Ontology:
Molecular function: metal ion binding
Biological process: cellular response to cadmium ion; cellular response to copper ion; cellular response to zinc ion; detoxification of copper ion; intracellular zinc ion homeostasis
Cellular component: cytoplasm; nucleus
Genetic constraint (gnomAD): Loss-of-function variants: 8 observed, 6.79 expected, observed/expected ratio (o/e) 1.18, 90% interval 0.68 to 1.85. That is too few expected variants to judge how well the gene tolerates losing a copy. Missense variants: 81 observed, 69.53 expected, observed/expected ratio (o/e) 1.16, 90% interval 0.97 to 1.4. Synonymous variants: 27 observed, 21.86 expected, observed/expected ratio (o/e) 1.24, 90% interval 0.91 to 1.69.
Homologues: Orthologues: chimpanzee MT4 (97% identical), macaque MT4 (97% identical), mouse Mt4 (90% identical), pig MT4 (90% identical), rat Mt4 (90% identical), dog MT4 (89% identical), rabbit MT4 (89% identical), guinea pig MT4 (87% identical), zebrafish mt2 (60% identical). Paralogues in human: MT1H (63% identical), MT1X (63% identical), MT2A (63% identical), MT1A (61% identical), MT1G (61% identical), MT1HL1 (60% identical), MT3 (60% identical), MT1B (58% identical), MT1F (58% identical), MT1M (55% identical), MT1E (32% identical).
Diseases named in the same sentence as MT4 in open-access papers:
MT4 is named in the same sentence as 36 diseases in open-access papers, as found by Europe PMC text mining. Sharing a sentence is not in itself a finding about the gene and the disease. The quoted sentences say what the papers report.
breast carcinoma (6 papers, 2012 to 2023). "Nevertheless, the pro-proliferative effect of MT4-MMP on breast cancer cells in vitro has been inhibited by erlotinib, and the presence of MT4-MMP in tumors was shown to be associated with more sensitivity to chemotherapy." (PMID 37373092, 2023). "In fact, in well-established xenografts of breast carcinoma, MT4-MMP in tumor cells promotes paracrine pericyte detachment from tumor vessels, thereby allowing cancer cell escape and intravasation into blood vessels and leading to metastatic spread." (PMID 37373092, 2023). "In contrast to its intrinsic non-proteolytic effect on EGFR activation and cell proliferation in 3D Matrigel, the enzymatic activity of MT4-MMP was still required for the early angiogenic switch during breast cancer progression." (PMID 37373092, 2023). "It is also worth noting that in human breast cancer, MT4-MMP transcription is also regulated by the methyltransferase hSED1A, which appears to be over-expressed in these circumstances." (PMID 37373092, 2023). "In all breast cancers, the MT4-MMP transcript was found to increase by 1.34-fold with a significant p-value." (PMID 37373092, 2023). "While MT4-MMP was inefficient in promoting breast cancer cell migration and invasion in vitro and in the 2D matrix, it promotes metastasis in vivo." (PMID 37373092, 2023). "MT4-MMP was first described in breast cancers, in which it has been more widely investigated compared to the other cancers." (PMID 30654475, 2019). "For instance, in breast cancer, MT4-MMP induces tumor growth and metastasis by stimulating angiogenesis in the tumor." (PMID 28926609, 2017). "In human breast cancer samples, a higher intensity of MT4-MMP immunostaining is observed in cancer cells compared to normal breast epithelial cells." (PMID 22822400, 2012). "The overexpression of MT4-MMP in the breast cancer cell line MDA-MB-231 enhances subcutaneous tumor growth and most importantly leads to lung metastasis when cells are inoculated in RAG-1 immunodeficient mice." (PMID 22822400, 2012). "The pro-angiogenic and pro-metastatic functions of MT4-MMP have been highlighted in breast cancer." (PMID 30654475, 2019). "Indeed, MT4-MMP was cloned for the first time from human breast carcinoma cells." (PMID 37373092, 2023). "For instance, MT4-MMP internalization was shown to be primarily dependent on Cdc42 and RhoA, and to a lesser extent on Rac1 in MDA-MB-231 cells, a human breast cancer cell line overexpressing the proteinase." (PMID 37373092, 2023). "In this field, particular attention should be given to the generation of functional blocking molecules for MT4-MMP and exploring their combination with EGFR inhibitors in breast cancer." (PMID 37373092, 2023). "Ultimately, they suggested that MT4-MMP plays a critical factor in the progression and metastasis of breast cancer." (PMID 38310435, 2023). "Regarding MT4-MMP involvement in tumor development, this protease was first detected in human breast carcinoma exerting pro-angiogenic and pro-metastatic functions." (PMID 37373092, 2023). "The contribution of MT4-MMP to tumor development has been further investigated in gastric cancer, colon cancer, head and neck cancer, and more deeply in breast cancer." (PMID 30654475, 2019). "Since 2006, special attention has been brought to the study of MT4-MMP, which has been identified in experimental models of mammary cancers as a driver of metastasis." (PMID 30654475, 2019). "Breast cancer xenografts with an inert form of MT4-MMP (E249A) were not able to induce early angiogenesis and have reduced growth potential when compared to xenografts producing the active form of the enzyme." (PMID 37373092, 2023). "Furthermore, the epigenetic regulation of MT4-MMP among other MMPs by the histone methyltransferase, hSETD1A, overexpressed in metastatic human breast cancer cell lines and patients has been demonstrated to drive breast cancer metastasis." (PMID 37373092, 2023).
breast carcinoma (continued). "Therefore, co-expression of MT4-MMP and HIF-1α may be considered as an indicator of breast cancer prognosis." (PMID 37373092, 2023). "While genomic profiling did not reveal a particular interest in MT4-MMP, immunohistochemistry studies have demonstrated its overexpression in breast cancers, suggesting possible alternative splicing in MT4-MMP transcripts in human cancers." (PMID 37373092, 2023). "In the context of tumorigenesis, MT4-MMP can form homodimers depending on Cys574 and the formation of disulfide bonds between the monomers both in transfected non-tumor MDCK and COS1 cells and in MD-MB-231 breast carcinoma cells." (PMID 37373092, 2023).
colon cancer (6 papers, 2018 to 2025). "MT4-MMP-mediated metastatic dissemination has been also pointed out in colon cancer and head and neck cancer." (PMID 30654475, 2019). "MT4, characterized by the overall low level of fecal metabolites, had a high abundance of Fusobacterium and Desulfovibrionaceae, which are known to be overrepresented in patients with colon cancer and ulcerative colitis and to be involved in inflammation." (PMID 29988433, 2018). "It is known that silencing hSED1A decreases MT4-MMP transcription, which impairs cell migration and invasion of tumor cells on lung tissue and colon cancer cells." (PMID 37373092, 2023). "We rescued hNDF knockout (KO) human SW480 colon cancer cells with wild-type hNDF, MT2, or MT4." (PMID 40430013, 2025). "Interestingly, restoration of caveolin-1 expression in metastatic HM-7 cells inhibits MT4-MMP localization to lipid rafts, thereby suppressing the metastatic phenotype of HM-7 colon cancer cells." (PMID 37373092, 2023). "MT4-MMP is expressed in lipid rafts of highly metastatic colon cancer cell line HM-7, but not in the parental lower metastatic cell line LS174T, suggesting a role of MT4-MMP in the metastatic dissemination of colon cancer." (PMID 30654475, 2019). "Interestingly, the restoration of caveolin-1 expression in metastatic HM-7 cells inhibits MT4-MMP expression in the lipid rafts, suppressing the metastatic phenotype of colon cancer cells." (PMID 30654475, 2019).
gastric cancer (4 papers, 2015 to 2023). A primary or metastatic malignant neoplasm involving the stomach. "This study highlighted an association of MT4-MMP expression with the depth of tumor invasion, lymph node metastasis and serosal involvement of gastric cancer patients." (PMID 30654475, 2019). "The aim of the present study was to investigate the expression and clinicopathological features of matrix metalloproteinase 17 (MMP17; also known as MT4-MMP) and MMP25 (also known as MT6-MMP) in gastric cancer." (PMID 25621036, 2015). "Notably, DNA methylation of some MT isoforms in gastric cancer, like MT1A, MT1B, MT1H, MT1M, MT3, and MT4, was higher than their paired normal tissue except remaining isoforms." (PMID 31380415, 2019).
atherosclerosis (3 papers, 2018 to 2023). A disease characterized by the build-up of fatty material and calcium deposition in the arterial wall resulting in partial or complete occlusion of the arterial lumen. "A study has reported that MT4 deficiency promotes the recruitment of monocytes and thus promotes atherosclerosis." (PMID 36743388, 2023). "MT4-MMP has been involved in inflammation and angiogenesis, contributing to associated pathologies such as osteoarthritis and atherosclerosis, as well as thoracic aortic aneurysms and dissection (TAAD)." (PMID 30654475, 2019). "Here, the authors report that MT4-MMP-deficiency increases the recruitment of patrolling monocytes to early atherosclerotic lesions, which accelerates atherosclerosis." (PMID 29500407, 2018). "Indeed, MT4-MMP cleaves αM integrin at the surface of crawling monocytes, inducing their detachment and the loss of their function in the regulation of atherosclerosis." (PMID 30654475, 2019). "CCR5 inhibition alleviates these effects by hindering the enhanced recruitment of MT4-MMP-null patrolling monocytes to early atherosclerotic lesions, thus blocking Mafb+AIM+ macrophage accumulation and atherosclerosis acceleration." (PMID 29500407, 2018). "Functionally, MT4-MMP-null Mafb+AIM+ peritoneal macrophages express higher AIM and scavenger receptor CD36, are more resistant to apoptosis, and bind acLDL avidly, all of which contribute to atherosclerosis." (PMID 29500407, 2018).
glioma (2 papers, 2019 to 2023). A benign or malignant brain and spinal cord tumor that arises from glial cells (astrocytes, oligodendrocytes, ependymal cells). "At a gene-level, only MT4 in the GliomaSE cohort was significantly associated with glioma across all three tests (p = 0.04)." (PMID 31350461, 2019). "MT4-MMP downregulation is unique to glioma because in other cancer cell lines (Jurkat or HeLa among others) MT4-MMP expression levels are higher." (PMID 37373092, 2023). "In contrast, MT4-MMP is downregulated in glioma development." (PMID 37373092, 2023). "Furthermore, it is described that MT4-MMP is predominantly expressed by glioma cells, instead of microglia, which is the key driver for the tumor cell invasion in the CNS." (PMID 37373092, 2023). "Moreover, brain invasion by glioma cells is very extensive locally with a large vascular development in which MT4-MMP could play an additional role." (PMID 37373092, 2023).
head and neck cancer (2 papers, 2019 to 2023). A primary or metastatic malignant neoplasm affecting the head and neck. "In fact, invadopodia formation and amoeboid movements, which are both crucial mechanisms to promote metastatic dissemination, are mediated by HIF1-α-induced MT4-MMP expression in head and neck cancer tumor cells." (PMID 37373092, 2023). "In this study, differential gene expression of MT4-MMP was found to increase by more than two folds in head and neck cancer, renal clear cell cancer, lung adenocarcinoma, and in lung squamous cancer." (PMID 37373092, 2023). "A link between hypoxia, EMT, and the regulation of MT4-MMP expression has been evidenced in head and neck cancer where SLUG contributes to HIF-1α dependent MT4-MMP." (PMID 37373092, 2023). "Generally, increased MT4-MMP activity is frequently detected in breast, colorectal, and head and neck cancer cells and fosters an invasive and metastatic phenotype." (PMID 37373092, 2023).
triple-negative breast carcinoma (2 papers, 2019). An invasive breast carcinoma which is negative for expression of estrogen receptor (ER), progesterone receptor (PR), and human epidermal growth factor receptor 2 (HER2). "Moreover, superimposition of EGFR and MT4-MMP has been observed in human triple-negative breast cancer (TNBC) patients." (PMID 30654475, 2019). "Similarly, triple-negative breast cancers with MT4-MMP, EGFR and RB-positive are sensitive to Erlotinib in combination with Palbociclib in PDX model." (PMID 31358010, 2019). "Interestingly, the overexpression of MT4-MMP in MDA-MB-231 cells (triple-negative breast cancer cell line) promotes cell proliferation in the 3D matrix in vitro and in subcutaneous xenografts." (PMID 30654475, 2019). "In sharp contrast, MT4-MMP has been reported to exert mitogenic effects on triple-negative breast cancer cells that are independent of its proteolytic activity." (PMID 30654475, 2019).
Arthritis (1 paper, 2019). Inflammation of a joint. "While the physiological functions of MT4-MMP are poorly understood, it has been involved in different pathological processes such as arthritis, cardiovascular disease, and cancer progression." (PMID 30654475, 2019).
breast adenocarcinoma (1 paper, 2019). "Immunohistochemistry staining revealed a higher expression of MT4-MMP in breast adenocarcinomas, while healthy breast tissues presented a negative to moderate positivity." (PMID 30654475, 2019).
fungal infection (1 paper, 2024). "Because MT4 reduced enterococci, which can contribute to the dissolution of epithelial E-cadherin from cell junctions during fungal infection, we also evaluated the integrity of the mucosal barrier by assessing the immunoreactivity pattern of E-cadherin." (PMID 39287438, 2024).
hepatocellular carcinoma (1 paper, 2023). A malignant tumor that arises from hepatocytes. "In peritumor and tumor samples of hepatocellular carcinoma, MT4-MMP-positive cells colocalized with macrophages expressing M2 phenotypic markers, while is absent in tumor cells, fibroblasts, or M1 macrophages." (PMID 37373092, 2023). "In addition, MT4-MMP-positive TAMs reduced, in a paracrine manner, E-cadherin expression in favor of mesenchymal N-cadherin, and vimentin in hepatocellular carcinoma cells, which is characteristic of the epithelial–mesenchymal transition (EMT) necessary for tumor metastasis." (PMID 37373092, 2023).
HIV-1 infection (1 paper, 2021). The type species of lentivirus and the etiologic agent of acquired immunodeficiency syndrome (AIDS). "Moreover, we detected the 11 changed miRNA in MT4 after HIV-1 infection by qPCR and found that miR-210 was also the most upregulated miRNA." (PMID 34965271, 2021).
lymphoma (1 paper, 2011). A malignant (clonal) proliferation of B- lymphocytes or T- lymphocytes which involves the lymph nodes, bone marrow and/or extranodal sites. "And including T-cell-originated lymphoma cell lines: Jurkat, Molt3, SupT1 and MT4, we tried to know common features leading to lymphoma formation." (PMID 23213546, 2011).
myopia (1 paper, 2017). "Such expression changes were evident, particularly in the late myopia dataset where a wide range of genes linked with oxidative stress were either up-regulated (GPX1, GSTA3, MT-4, APOA1, OTUB, PTGDS, HSPB1, HSPB2) or down-regulated (XHD, SLC40A1, TF, SOD3, HPGDS, BCMO1)." (PMID 28852117, 2017).
osteoarthritis (1 paper, 2019). A noninflammatory degenerative joint disease occurring chiefly in older persons, characterized by degeneration of the articular cartilage, hypertrophy of bone at the margins and changes in the synovial membrane. "All these data imply the role of MT4-MMP in the regulation of aggrecan processing under inflammatory contexts, and open new therapeutic perspectives in osteoarthritis treatment." (PMID 30654475, 2019).
ovarian carcinoma (1 paper, 2015). A malignant neoplasm originating from the surface ovarian epithelium. "Consistent with previous studies, we determined the role of MAPK signaling in MT-4-induced ovarian cancer apoptosis." (PMID 25874627, 2015). "Substitution of the 4′-hydroxyl group of moscatilin (4,4′-dihydroxy-3,3′,5′-trimethoxybibenzyl) with a methoxy group led to the synthesis of MT-4, which was the most effective derivative against ovarian cancer cell, A2780, with a GI50 of 0.04 μM." (PMID 25874627, 2015). "In addition, MT-4 induces apoptosis through a caspase-dependent pathway initiated by tubulin destabilization and p38 activation in ovarian cancer cells in vitro and in vivo." (PMID 25874627, 2015). "Immunoblotting analysis was carried out to evaluate the effect of MT-4 on ovarian cancer." (PMID 25874627, 2015).
thyroid nodule (1 paper, 2023). A small circumscribed mass in the THYROID GLAND that can be of neoplastic growth or non-neoplastic abnormality. "Analysis of data demonstrated increased levels of MT4-MMP (PTC: 4.90±1.35, MNG: 4.89±1.37, and healthy: 3.13±1.42) and MT6-MMP (PTC: 8.29±2.50, MNG: 7.34±2.09, and healthy:5.01±2.13) in thyroid nodules by comparison with healthy subjects (P<0.05)." (PMID 38310435, 2023). "Based on the critical role of MT4-MMP and MT6-MMP in carcinogenesis, we focused on MT4-MMP and MT6-MMP circulating levels in patients with thyroid nodules." (PMID 38310435, 2023).